PRAME (PRAME nuclear receptor transcriptional regulator)
Description:
Substrate-recognition component of a Cul2-RING (CRL2) E3 ubiquitin-protein ligase complex, which mediates ubiquitination of target proteins, leading to their degradation. The CRL2(PRAME) complex mediates ubiquitination and degradation of truncated MSRB1/SEPX1 selenoproteins produced by failed UGA/Sec decoding. In the nucleus, the CRL2(PRAME) complex is recruited to epigenetically and transcriptionally active promoter regions bound by nuclear transcription factor Y (NFY) and probably plays a role in chromstin regulation. Functions as a transcriptional repressor, inhibiting the signaling of retinoic acid through the retinoic acid receptors RARA, RARB and RARG: prevents retinoic acid-induced cell proliferation arrest, differentiation and apoptosis.
Synonyms: OIP-4; MAPE; OIP4; CT130
Tractability: Antibody: UniProt places it where antibodies can reach, with high confidence; its Gene Ontology location is reachable by antibodies, with high confidence. PROTAC: ubiquitination databases record sites on it.
Gene: Protein-coding gene on chromosome 22 (22,547,701 to 22,559,361, reverse strand). Ensembl gene ENSG00000185686.
Subcellular location: Nucleus; Chromosome; Cytoplasm; Golgi apparatus; Cell membrane
Subcellular location (Human Protein Atlas): Nucleoplasm; Plasma membrane
Gene Ontology:
Molecular function: nuclear retinoic acid receptor binding; protein binding; ubiquitin-like ligase-substrate adaptor activity
Biological process: negative regulation of apoptotic process; negative regulation of cell differentiation; negative regulation of DNA-templated transcription; negative regulation of retinoic acid receptor signaling pathway; positive regulation of cell population proliferation; proteasome-mediated ubiquitin-dependent protein catabolic process; protein polyubiquitination; ubiquitin-dependent protein catabolic process via the C-end degron rule pathway; protein ubiquitination
Cellular component: chromatin; chromosome; Cul2-RING ubiquitin ligase complex; cytoplasm; Golgi apparatus; nucleus; plasma membrane
Genetic constraint (gnomAD): Loss-of-function variants: 21 observed, 33.61 expected, observed/expected ratio (o/e) 0.62, 90% interval 0.44 to 0.9. The upper end of that interval is the gene's LOEUF score, 0.9, which puts it in group 3 of 6, group 1 being the genes least tolerant of losing a copy. Missense variants: 651 observed, 650.05 expected, observed/expected ratio (o/e) 1, 90% interval 0.94 to 1.07. Synonymous variants: 274 observed, 263.2 expected, observed/expected ratio (o/e) 1.04, 90% interval 0.94 to 1.15.
Homologues: Orthologues: chimpanzee PRAME (96% identical), macaque PRAME (94% identical), dog PRAME (68% identical), pig PRAME (61% identical), zebrafish si:ch73-174h16.4 (25% identical). Paralogues in human: PRAMEF12 (50% identical), PRAMEF7 (50% identical), PRAMEF8 (50% identical), PRAMEF15 (48% identical), PRAMEF6 (48% identical), PRAMEF20 (48% identical), PRAMEF5 (48% identical), PRAMEF27 (48% identical), PRAMEF4 (48% identical), PRAMEF9 (48% identical), PRAMEF11 (48% identical), PRAMEF25 (48% identical), and 12 more.
Diseases named in the same sentence as PRAME in open-access papers:
PRAME is named in the same sentence as 162 diseases in open-access papers, as found by Europe PMC text mining. Sharing a sentence is not in itself a finding about the gene and the disease. The quoted sentences say what the papers report.
melanoma (225 papers, 2004 to 2026). A malignant, usually aggressive tumor composed of atypical, neoplastic melanocytes. "While PRAMEL12, a cancer/testis antigen PRAME (preferentially expressed antigen of melanoma) family member, is implicated in spermatogenesis, its specific functions remain poorly understood." (PMID 41866036, 2026). "Based on their findings, they suggested categorizing PRAME expression into diagnostic ranges: ≤25% favoring benign nevi, 26–75% as indeterminate, and >75% suggestive of melanoma." (PMID 41153267, 2025). "An exciting avenue of research is the ongoing exploration of BiTEs targeting other melanoma-associated antigens, such as the PRAME (preferentially expressed antigen in melanoma) antigen." (PMID 39857682, 2025). "One immunohistochemical stain of recent increased utilization is PRAME (PReferentially expressed Antigen in MElanoma), a tumor-associated antigen originally isolated from a melanoma patient expressed in most melanomas." (PMID 41562714, 2025). "One immunohistochemical stain frequently utilized is PRAME (PReferentially expressed Antigen in MElanoma), a tumor-associated antigen expressed in most melanomas." (PMID 41562714, 2025). "PRAME has become a widely used marker that facilitates melanoma diagnosis due to its association with many cellular processes relevant to tumor and metastasis development." (PMID 40700516, 2025). "Our study aimed to evaluate the diagnostic utility of PRAME expression in differentiating melanoma from various melanocytic lesions, including dysplastic nevi, congenital nevi, blue nevi, and Spitz nevi." (PMID 41153267, 2025). "In recent years, immunohistochemistry focusing on PRAME (preferentially expressed in melanoma) has emerged as a valuable diagnostic tool for melanocytic tumors." (PMID 39625060, 2025). "PRAME (PReferentially expressed Antigen in Melanoma) is a melanoma-associated antigen that was first isolated by autologous T-cells in a patient with metastatic melanoma." (PMID 40941765, 2025). "The observation of diffuse PRAME expression should prompt further molecular analysis to explore potential underlying melanoma‐compatible mutations, particularly in appropriate clinical settings." (PMID 39625060, 2025). "mRNA vaccines encoding PRAME antigens have been tested in preclinical or early-phase clinical trials for melanoma and other cancers." (PMID 39451258, 2024). "It is known that both PRAME activation and 5hmC loss play important roles in driving melanoma development." (PMID 39091741, 2024). "PRAME (PReferentially expressed Antigen in Melanoma) immunohistochemistry (IHC) has proven its diagnostic utility in differentiating between benign melanocytic tumors and malignant melanocytic tumors." (PMID 39335694, 2024). "Recently, IHC staining of preferentially expressed antigen in melanoma (PRAME), a tumor-associated antigen, was widely explored to distinguish between benign and malignant melanocytic tumors." (PMID 39408752, 2024). "PRAME (PReferentially expressed Antigen in MElanoma) is a tumor-associated antigen first identified in tumor-reactive T-cell clones derived from a patient with metastatic melanoma." (PMID 39727621, 2024). "A recent paper by Kaczorowski and colleagues has reported loss of 5hmC and a concomitant increase PRAME expression in melanoma, which is consistent with our findings." (PMID 39091741, 2024). "Tumor-associated antigens, such as PRAME (Preferentially Expressed Antigen in Melanoma), offer promising avenues for enhanced diagnostic precision, prognostic assessment, and targeted immunotherapy." (PMID 39451258, 2024). "TET2-overexpression (OE) in cultured human melanoma cell lines resulted in a significant decrease in PRAME expression and this reduction is associated with increased 5hmC levels." (PMID 39091741, 2024). "Melanoma-associated antigen PRAME, or Preferentially expressed Antigen in Melanoma, has emerged as a promising target in cancer research, particularly in the context of melanoma." (PMID 38338862, 2024).
melanoma (continued). "Conversely, A. Alomari identified PRAME positivity as a possible diagnostic pitfall in spitzoid melanoma diagnosis due to the cases of diffusely positive benign spitzoid lesions, which are likely just in a proliferative state." (PMID 39451258, 2024). "PRAME expression has been shown in numerous studies to be highly associated with an unfavorable melanoma prognosis." (PMID 39451258, 2024). "For example, PRAME (preferentially expressed antigen in melanoma) proved to be useful in evaluating melanoma in situ associated with melanocytic cells exhibiting nevoid features or in cases of invasive tumors associated with dermal nevic cells." (PMID 36980327, 2023). "Numerous articles have examined the expression profiles of PRAME in malignant melanoma and have demonstrated its diagnostic utility." (PMID 38132219, 2023). "As its name suggests, PRAME was first identified in melanoma and was shown to be causally involved in the tumourigenic process in melanoma." (PMID 36980267, 2023). "Several studies suggested that PRAME is associated with the epigenetic regulation of acetylation in human malignancies like seminomas and melanoma." (PMID 36910848, 2023). "PRAME was first reported as a tumor-associated antigen expressed in malignant melanoma recognized by cytotoxic T lymphocytes." (PMID 38132219, 2023). "Other peptides of interest included peptides previously reported as immunogenic and derived from PReferentially expressed Antigen in MElanoma (PRAME), Melanoma associated antigen A1 (MAGEA1), and Ephrin receptors proteins." (PMID 37637064, 2023). "Existing studies had implicated that the function of PRAME has been mainly correlated with melanoma and several hematological cancers." (PMID 36910848, 2023). "Due to its nature as a cancer/testis antigen, PRAME expression has been recognized as a useful diagnostic marker for several types of malignant tumor, especially malignant melanomas." (PMID 38132219, 2023). "Analyzing the specificity of tumor-reactive T-cell clones derived from a patient with metastatic cutaneous melanoma, a tumor-associated antigen was recently identified, known as PRAME (preferentially expressed antigen in melanoma)." (PMID 35565234, 2022). "PRAME nuclear receptor transcriptional regulator gene encodes an antigen that is preferentially expressed in human melanomas." (PMID 35167614, 2022). "PRAME (PReferentially expressed Antigen in MElanoma) is a tumor-associated antigen that was recently found to be expressed by malignant melanocytic lesions but not by benign ones, thus resulting useful in this diagnostic field." (PMID 34508017, 2022). "PRAME is also a tumor-associated antigen and has been a promising immunohistochemical marker in melanoma." (PMID 35646893, 2022). "PRAME is a gene encoding an HLA-24-restricted antigenic peptide presented to autologous melanoma protein." (PMID 35788450, 2022). "PRAME (preferentially expressed antigen in melanoma) is a tumor-associated antigen identified through the T-cell clones obtained from a patient with metastatic CM and encoded by the PRAME gene located on chromosome 21q11.22." (PMID 35682589, 2022). "PRAME (preferentially expressed antigen in melanoma) is a tumor-associated antigen expressed by some neoplasms, which recently emerged as a novel immunohistochemical marker for the diagnosis of CM." (PMID 35328198, 2022). "Preferentially expressed antigen in melanoma (PRAME) is an antigen that increases metastatic susceptibility when expressed in uveal melanoma cells." (PMID 34195690, 2021). "PRAME (PReferentially expressed Antigen in MElanoma) is a tumor-associated antigen recently identified in some neoplasms, including myxoid liposarcoma, synovial sarcoma, and MM." (PMID 34195089, 2021). "In this study, we investigated the expression and prognostic significance of PRAME expression in thin melanomas and assessed its diagnostic utility in the distinction from SDN." (PMID 34359765, 2021).
melanoma (continued). "PRAME is a testis- and melanoma-associated transcriptional repressor that inhibits retinoic acid signaling." (PMID 34968235, 2020). "Preferentially expressed antigen in melanoma (PRAME) was first discovered in melanomas and it was associated with cytotoxic T cell activation." (PMID 28630682, 2017). "PRAME expression was associated with shorter time to metastasis and melanoma specific mortality in Class 2 tumors (P = 0.01 and P = 0.02, respectively)." (PMID 27486988, 2016). "APOD (apolipoprotein D) and ABCA8 (ATP-binding cassette, sub-family A member 8) encode transporter proteins while PRAME (preferentially expressed antigen in melanoma) and CCL19 (chemokine ligand 19) genes are involved in immunoregulatory processes." (PMID 26961242, 2016). "The preferentially expressed antigen of melanoma (PRAME) was initially identified as a tumor-associated antigen recognized by cytotoxic T lymphocytes against a melanoma surface antigen." (PMID 27391090, 2016). "The gene encoding preferentially expressed antigen in melanoma (PRAME) is not only involved in melanoma progression but is also implicated in ovarian cancer, neoplasia and breast cancer." (PMID 21294715, 2011). "PRAME, or preferentially expressed antigen in melanoma, was originally identified as a gene encoding a HLA-A24 restricted antigenic peptide presented to autologous tumour-specific cytotoxic T lymphocytes derived from a patient with melanoma." (PMID 20799951, 2010). "TCR-T therapies have been developed to target a range of melanoma-associated antigens expressed in UM, including PRAME (preferentially expressed antigen in melanoma), MAGE-C2 (melanoma-associated antigen C2), SLC45A2, and MART-1 (melanoma antigen recognized by T cells-1)." (PMID 40725830, 2025). "Therefore, despite the immunohistochemical similarities between malignant melanomas and sarcomas, PRAME remains a good diagnostic marker for melanomas." (PMID 39862670, 2025). "Similarly, in melanoma, high PRAME expression is often associated with more aggressive tumor behavior and a poorer clinical outcome." (PMID 40868240, 2025). "PRAME, indeed, was initially identified as a gene encoding antigens presented by HLA-A*24, capable of activating tumor-specific cytotoxic T lymphocytes (CTLs) derived from melanoma patients." (PMID 40611330, 2025). "Additionally, Preferentially Expressed Antigen in Melanoma (PRAME) serves as both a diagnostic and prognostic marker, primarily used in the assessment of melanoma." (PMID 40870546, 2025). "Increased PRAME expression in melanomas has also been linked with poor prognosis, and this might explain the co-occurrence of this marker with DNMTs." (PMID 38541782, 2024). "In addition, recent studies, including one investigating PRAME immunohistochemistry in dedifferentiated and undifferentiated melanoma, have strengthened the diagnostic value of PRAME." (PMID 38338862, 2024). "In melanoma, positive associations between expression of PRAME and DNMT3A and DNMT3B were seen." (PMID 38541782, 2024). "The increased mutational load in V600K melanomas may indicate a more immunogenic environment, which could influence PRAME expression levels, but this relationship needs to be studied further." (PMID 39451258, 2024). "In addition to its diagnostic potential, PRAME is increasingly being recognised as a prognostic marker in melanoma." (PMID 38338862, 2024). "We hypothesized that inactivation of TET and the resulting loss of 5hmC marks might be trigger for PRAME overexpression during melanoma pathogenesis; in this study we test this idea." (PMID 39091741, 2024). "Class 1 UM is associated with upregulation of PReferentially expressed Antigen in MElanoma (PRAME), and class 2 UM mutations are associated with mutations or biallelic inactivation of BRCA1 (breast cancer type 1 susceptibility protein)-associated protein 1 (BAP1)." (PMID 37626310, 2023).
melanoma (continued). "This study aimed to examine the expression profiles of preferentially expressed antigen in melanoma (PRAME), a cancer/testis antigen, and assess its diagnostic and therapeutic applications in CIS, given that its expression in UC has been minimally studied and has not yet been analyzed in CIS." (PMID 38132219, 2023). "Since the (partial) loss of conventional melanocytic markers in primary melanomas and metastases with rhabdoid differentiation makes histopathologic diagnosis challenging, additional immunostaining for PRAME could facilitate diagnosis." (PMID 35645230, 2022). "Approximately, preferentially expressed antigen in melanoma (PRAME), a tumor-associated antigen is expressed in around 80% of medulloblastomas, and it also exhibited promising results when engineered into CAR T-cell targets in orthotopic medulloblastoma models." (PMID 33673696, 2021). "Accordingly, in this study, we identified preferentially expressed antigen in melanoma (PRAME), a type of cancer-testis antigen, as a novel diagnostic marker of TSQCC for the first time, based on comprehensive mRNA expression analysis and immunohistochemical validation." (PMID 32704057, 2020). "Herein, we found that preferentially expressed antigen in melanoma (PRAME) may be a novel TSQCC-specific diagnostic marker." (PMID 32704057, 2020). "Indeed, it has been recently associated with PRAME (preferentially expressed antigen of melanoma) upregulation and colony formation, which is associated with metastatic potential in melanoma cell line studies." (PMID 31383874, 2019). "In addition we observed a significant SCD5-dependent down-regulation of Preferentially Expressed Antigen in Melanoma (PRAME), a melanoma antigen causally implicated in tumor transformation and acting as a dominant inhibitor of the retinoic acid receptor (RAR) pathway." (PMID 29484133, 2018). "PRAME, as one of the CT genes, first identified as an antigen-encoding gene related to immunity in a melanoma cell line, is expressed predominantly in normal testis and melanoma, lung squamous cell carcinoma, and acute leukemia, and at much lower levels in the ovary and other tissues." (PMID 21347312, 2011). "PRAME (Preferentially Expressed Antigen in Melanoma) is increasingly used as an immunohistochemical marker in the evaluation of melanocytic lesions; however, its expression in benign melanocytic proliferations remains incompletely characterized." (PMID 41892080, 2026). "Initially discovered during research on melanoma cell lines, PRAME has since garnered attention as a promising immunotherapeutic target." (PMID 40868240, 2025). "The incorporation of novel immunohistochemical markers, such as PRAME, offers a promising avenue to reduce diagnostic ambiguity and improve precision in distinguishing CCS from melanoma and other histologically similar neoplasms." (PMID 40004764, 2025). "Since PRAME expression is retained in nearly all melanoma cells within PRAME-positive tumors, even small satellite deposits can be identified more easily, potentially improving staging accuracy." (PMID 40868240, 2025). "Melanomas are traditionally diffusely positive for PRAME, which is defined as expression in >75% of tumour cells." (PMID 40507250, 2025). "PRAME is an immunohistochemical marker that has become increasingly important in the routine diagnosis of melanoma in recent years." (PMID 40941765, 2025). "Since NB has been proved to overexpress the preferentially expressed antigen of melanoma (PRAME), HLA-A2 restricted PRAME-SLL specific αβTCR-T cells were generated." (PMID 40611330, 2025). "These cases confirm the diffuse PRAME expression in dedifferentiated melanomas, including transdifferentiated subsets." (PMID 39625060, 2025). "Unlike gp100, which is more commonly expressed in cutaneous melanoma, PRAME has shown promise as a target in cutaneous melanoma and other melanoma subtypes." (PMID 39857682, 2025).